BRIP1 (BRCA1 interacting DNA helicase 1)
Diseases named in the same sentence as BRIP1 in open-access papers (continued):
Sharing a sentence is not in itself a finding about the gene and the disease.
tumor (continued). "High expression of BRIP1 was found in the tumor tissues, whereas low to medium expression of BRIP1 was noticed in the corresponding normal tissues." (PMID 36907870, 2023). "Here, we review the molecular features and hereditary tumor risk associated with several moderate-penetrance genes in EOC that are involved in the homologous recombination repair pathway, i.e., ATM, BRIP1, NBN, PALB2, and RAD51C/D." (PMID 36233090, 2022). "In germline BRCA1/BRCA2/RAD51C/RAD51D/BRIP1 PVs, 44.4% (24/54) had a positive FH compared to 11.3% (28/249) of sporadic tumours (p < 0.001)." (PMID 34503154, 2021). "BARD1 and BRIP1 are both tumor suppressors, that act in the repair of double-stranded DNA damage, with proteins, interact with BRCA1." (PMID 34768979, 2021). "Functional assays validated further the physiological relevance of BRIP1 in tumour malignancy, and siRNA‐mediated BRIP1 knockdown significantly reduced BC cell motility by targeting key motility‐associated genes." (PMID 32888398, 2020). "LOH or AST mutation was detected in at least one tumor with PALB2, ATM, RAD51D, BARD1, BRIP1, RAD51C, or NF1 germline mutation." (PMID 32566746, 2020). "In the present study, RNAi‐inhibited BRIP1 down‐regulated Ras GTPases significantly by (−3.9) fold and subsequently suppressed tumour cell invasion." (PMID 32888398, 2020). "So far, limited results disclosed that the BRIP1 signature was prognostic for tumor stage, grade, and metastasis." (PMID 32587640, 2020). "BRIP1 is a tumor suppressor gene interacting with another known DNA repair gene, BRCA-1 (Breast Cancer gene 1), involved in repair by homologous recombination." (PMID 31064327, 2019). "BRIP1 interactions related to BRCA1 function suggested that BRIP1 have attracted the attention as a candidate tumor suppressor gene." (PMID 30975222, 2019). "Significant, tumour-specific loss of heterozygosity occurs in nine genes (ATM, BAP1, BRCA1/2, BRIP1, FANCM, PALB2 and RAD51C/D)." (PMID 26689913, 2015). "FANCJ, also known as the BRCA1-associated C-terminal helicase (BACH1) and the BRCA1-interacting protein (BRIP1), is a 5′-to-3′ DNA helicase that serves as a tumor suppressor and as a mediator of chromosomal stability." (PMID 26336824, 2015). "The nuclear BRCA1-interacting protein 1 (BRIP1; also referred to as BRCA1-associated C-terminal helicase, BACH1) directly binds the BRCT-motif containing domain of BRCA1, thus likely contributing to its DNA repair and tumour suppressor functions." (PMID 17504528, 2007). "Furthermore, BRIP1 (also known as BACH1) is a DNA helicase which acts as a potential tumor suppressor." (PMID 40727930, 2025). "BRIP1 was expressed in both tumor and adjacent tissue (the paired adjacent normal tissue to tumor)." (PMID 36932143, 2023). "Regarding the female dogs, we sequenced 79 BC-related genes, and those with high number of variants shared by tumor fragments and plasma were GATA3 and mTOR (missense), SFRP1 (frameshift insertion), BRCA2 (multi hit), FOXC2, ATM, TGFBR3, and BRIP1 (missense and multi hit mutations)." (PMID 34680380, 2021). "Among BRCA1/2 wild-type tumors, both BRIP1-mutated tumors were Sig3 positive while the RAD51C deleted tumor was Sig3 negative." (PMID 34552099, 2021). "In addition, to providing a better understanding of the mechanisms that underpin BRIP1‐mediated tumour cell invasion, this study has validated BRIP1 as a target gene that can be used to design efficient therapeutic strategies against BC." (PMID 32888398, 2020). "Based on these observations, we hypothesized that beyond its function as a DNA repair gene, BRIP1 plays a novel role in tumour cell invasion/metastasis." (PMID 32888398, 2020).
tumor (continued). "Our results indicated that germline truncation and missense variants in several genes were under selection in the tumour, with ATM, BRCA1, BRCA2 and RAD51C determined as significant from both truncation and missense analyses and BAP1, BRIP1, FANCM, PALB2 and RAD51D from truncation analysis alone." (PMID 26689913, 2015). "However, BRIP1 hasbeen shown to have a dual function of an oncogene and a tumor suppressor." (PMID 39430039, 2023). "One explanation could be the absence of biallelic inactivation of the BRIP1 gene, meaning such tumours were not BRIP1-protein-deficient and, therefore, HRR proficient." (PMID 36765687, 2023). "Similarly, knockout of COPS2 or BRIP1 achieved significant reduction of tumor burden." (PMID 36333584, 2022). "Collectively, although BRIP1 is considered as a tumour suppressor gene, it is amplified in sporadic cancers, thus supporting our previous 7 and current findings, suggesting that BRIP1 amplification in sporadic cancers could explain the oncogenic role of BRIP1." (PMID 32888398, 2020). "Thus, BRIP1 may function as tumor suppressor by affecting these tumor suppressive signaling pathways in the mammary glands." (PMID 24040146, 2013). "BRIP1, also known as BACH1 or FANCJ, interacts with BRCA1 and plays a role in DNA repair and tumor suppression." (PMID 41473825, 2025). "Although BRIP1 has been primarily investigated in the context of germline susceptibility, emerging studies indicate that altered expression of DDR-related genes at the tumor level may influence cancer aggressiveness and patient outcomes, even in sporadic cancers." (PMID 41597333, 2025). "Importantly, these findings suggest a correlational rather than a strictly independent prognostic role, indicating that BRIP1 expression may reflect underlying tumor biology rather than act as a standalone prognostic determinant." (PMID 41597333, 2025). "A review of the tumor CGP results revealed that two of these VUS alterations, one in ATM and one in BRIP1, were identified, but classified as benign and filtered from the final report." (PMID 35962742, 2023). "BRIP1 expression had a significant correlation with CNV and DNA methylation in 23 tumor types and 16 tumor types, respectively." (PMID 37153833, 2023). "Since we have detected potentially actionable PV/LPV for PARP inhibitor therapy in BRIP1 and RAD51C genes, the final percentage of actionable detected PV/LPV with germline genotyping was 66.6% (28/42), and with tumor genotyping 97.6% (41/42)." (PMID 35326583, 2022). "Four of these patients (11.8%) carried a possible germline PV/LPV detected in the BRCA1, RAD51C, BRIP1, or PTEN gene in the tumor sample." (PMID 35326583, 2022). "While BRIP1 represented the highest confidence hit predicted by PARIS, analysis of human tumor samples highlighted a consistent upregulation of FA genes in a low-ALDH2 expression background." (PMID 34454516, 2021). "It has been found that RPS6KB1, BRIP1, TRIM37, PPM1 D and other tumor-related genes are located in this region." (PMID 34659555, 2021). "As a result, we found two genes, BRIP1 and BARD1, that are involved in the HR pathway and show high expression only in the HRD tumor population." (PMID 32719318, 2020). "FANCJ (originally named BRCA1 interacting C-terminal helicase (BACH1) or BRCA1 interacting helicase (BRIP1) was first discovered by its physical interaction with BRCA1, a known tumor suppressor and mediator of double strand break (DSB) repair." (PMID 25374583, 2014). "We analyzed the ROC curves for all previously known potential factors, including age, tumor size, hemoglobin, along with our potential markers: BRCA1, BRCA2, RAD51, FANCD2, BLM and BRIP1." (PMID 24708616, 2014). "BRIP1 plays an important role in controlling BRCA1-dependent DNA repair, DNA damage–induced G2-M checkpoint control, and possibly tumor suppression." (PMID 24040146, 2013).
tumor (continued). "BRCA2 mutations occur in 5–10% of prostate cases, and RAD51C/RAD51D, BRIP1, or BARD1 defects may broaden eligibility across tumor types." (PMID 40864792, 2025). "Our investigation aims to unravel potential associations with other non-BC or non-OC tumour types with pathogenic or likely pathogenic mutations (hereinafter, PVs) in the RAD50, RAD51C, RAD51D, and BRIP1 genes." (PMID 40282418, 2025). "In addition, FOXM1 is an upstream regulator of various DNA damage repair genes such as XRCC1, BRCA2, RAD51, BRIP1 and NBS1, thereby enabling the tumor cells to resist the action of the genotoxic agents." (PMID 37025658, 2023). "As recently reported, an NGS profiling including HR genes (BARD1, BRIP1, PALB2, RAD51C, and RAD51D) could improve the rate of tumor with HRD by 5–6%, identifying patients who may mostly benefit from PARPi therapy." (PMID 35406410, 2022). "If PV/LPV in RAD51C and BRIP1 genes, besides BRCA genes, are also considered as potentially actionable for treatment with PARP inhibitors, then a total of 42 potentially actionable PV/LPV were detected by tumor or germline genotyping." (PMID 35326583, 2022). "While BRCA1 and BRIP1 work as tumour suppressor genes, when BRIP1 fails to bind BRCA1 in certain conditions, cells become sensitive to different genotoxic stresses with aberrant homologous DNA repair function." (PMID 32888398, 2020). "Notably, other G4 helicases such as Blm, Wrn, and Brip1/Fancj were also expressed but not differentially expressed in tumor versus normal cerebellum." (PMID 40854122, 2025). "Nine cases with germline variants in HR-related genes PALB2, BRCA1, RAD51C, FAN1 and CHEK2 also showed evidence of enrichment of the germline variant in the tumor, while the other 12 cases with HR-related gene variants (seven FAN1, three CHEK2, one BRIP1, one NBN) did not." (PMID 33917078, 2021). "In addition, BRIP1 might contribute to BC bone metastasis by switching the SMAD pathway; (SMAD4 was down‐regulated by (−3.5) fold) from the known tumour suppression role to pro‐metastatic one." (PMID 32888398, 2020). "BRIP1, a DNA‐dependent ATPase and a 5'‐3' helicase that belongs to the DNA‐dependent RecQ DEAH helicase family, interacts with BRCA1 and is involved in double‐stranded DNA breaks (DSB) repair during the G2‐M phase of the cell cycle as well as in tumour suppression." (PMID 32888398, 2020). "The BRIP1-knockdown cells did not induce tumor formation in nude mice." (PMID 24040146, 2013). "BRIP1 expression was analyzed in 60 CRC tissues, and its expression level was not significantly different between tumor and paired adjacent non-tumorous tissues (p = 0.57)." (PMID 41597333, 2025). "Although BRIP1 interacts with BRCA1 to regulate cell cycle and DNA repair mechanisms, the role of BRIP1 in mediating tumour growth and progression has not been examined yet." (PMID 32888398, 2020).
CNS tumors (1 paper, 2024). "The most commonly overexpressed genes in CNS tumors included TOP2A (67%), BIRC5 (59%), CDK4 (50%), BRIP1 (49%), NOTCH1 (41%), SMO (39%), and TP73 (39%)." (PMID 38347552, 2024).
gynecological tumors (1 paper, 2023). "Furthermore, it was worth mentioning that the expression of BRIP1 was upregulated in almost gynecological tumors which indicates BRIP1 was potentially essential in gynecological oncology." (PMID 36932143, 2023).
BRIP1 also shares sentences with these, for which no sentence is quoted: hereditary cancer (8 papers); breast and (7); hereditary breast and ovarian cancer syndrome (6); familial breast cancer (5); Bloom syndrome (4); bone marrow failure (4); genetic disease (4); Li-Fraumeni syndrome (4); lymphoma (4); Warsaw breakage syndrome (4); osteosarcoma (3); adenocarcinoma (2); fallopian tube cancer (2); Fanconi anemia complementation group C (2); Hereditary breast cancer (2); hereditary cancer-predisposing syndrome (2); hereditary leiomyomatosis (2); invasive carcinoma (2); lung squamous cell carcinoma (2); medulloblastoma (2); non-small cell lung carcinoma (2); Pan (2); polyposis (2); stomach cancer (2); thyroid cancer (2); xeroderma pigmentosum group D (2); acute myeloid leukemia (1); adenocarcinoma of the small intestine (1); adenomatous colon polyp (1); autosomal recessive disease (1).
A further 63 diseases each share a sentence with BRIP1 in 1 paper.